LINC01645 (long independently transcribed non-coding RNA 1645)
Gene: Long non-coding RNA gene on chromosome 1 (177,351,049 to 177,459,903, forward strand). Ensembl gene ENSG00000224968.
Diseases named in the same sentence as LINC01645 in open-access papers:
LINC01645 is named in the same sentence as 1 disease in open-access papers, as found by Europe PMC text mining. Sharing a sentence is not in itself a finding about the gene and the disease. The quoted sentences say what the papers report.
gastric cancer (1 paper, 2021). A primary or metastatic malignant neoplasm involving the stomach. "The results demonstrated that higher expression levels of LINC01714, ZNF192P1, AC079760.2, LINC01645, EMX2OS, and AC114489.2 were significantly associated with the poor survival of gastric cancer patients." (PMID 34731149, 2021). "A total of 63 prognostic-associated eRNAs in gastric cancer were identified, the top 6 eRNAs were LINC01714, ZNF192P1, AC079760.2, LINC01645, EMX2OS, and AC114489.2." (PMID 34731149, 2021).